BRCA2 (BRCA2 DNA repair associated)
Diseases named in the same sentence as BRCA2 in open-access papers (continued):
Sharing a sentence is not in itself a finding about the gene and the disease.
chondrosarcoma (1 paper, 2025). A malignant cartilaginous matrix-producing mesenchymal neoplasm arising from the bone and soft tissue. "Other inconsistencies, such as the fact that a BRCA2 frameshift insertion in a patient with chondrosarcoma was not called in the panel due to a significantly lower TVF than in MASTER 1, are more likely due to sample preparation issues during the hybridization or enrichment process." (PMID 39794422, 2025).
choroidal melanoma (1 paper, 2023). Malignant tumor of melanocytes of the choroid. "The development of choroidal melanomas is also associated with breast cancer type 2 susceptibility protein (BRCA2) and BRCA-associated protein 1 (BAP1) genes." (PMID 36662495, 2023).
clear cell cervical adenocarcinoma (1 paper, 2022). "Discussion regarding options for treatment of recurrent cervical clear cell carcinoma included traditional systemic chemotherapy regimens as well as consideration of previous tumor genomics result that demonstrated a somatic BRCA2 mutation." (PMID 36330376, 2022). "In this patient with a distant recurrence of clear cell cervical adenocarcinoma with a somatic BRCA2 mutation, treatment with single-agent olaparib resulted in a durable response of 14 months with limited toxicity." (PMID 36330376, 2022).
cleft lip (1 paper, 2021). Congenital defect in the upper lip where the maxillary prominence fails to merge with the merged medial nasal prominences. "While little is known about how DDR functions during palate development, recent studies have shown that while it is modest, there are BRCA1 and BRCA2 variants in non-syndromic cleft lip and palate patients." (PMID 33854442, 2021).
cleft palate (1 paper, 2021). Cleft palate is a fissure type embryopathy that affects the soft and hard palate to varying degrees. "An ectomesenchymal-specific deletion of Brca1 or Brca2 resulted in cleft palate due to attenuation of cell survival." (PMID 33854442, 2021). "The aim of this study is to investigate the mechanistic connection(s) between a dysfunctional DDR, due to disruption of BRCA1/BRCA2 and cleft palate, using pharmacological and mouse genetic approaches to dissect the etiology of this craniofacial malformation." (PMID 33854442, 2021). "Our data indicate that maintaining genomic stability through the BRCA1 and BRCA2 DDR machinery may be key in preventing cleft palate." (PMID 33854442, 2021). "Because cell death in pre-migratory neural crest cells frequently leads to craniofacial abnormalities, one might predict that increased cell death in pre-migratory neural crest cells may lead to cleft palate in Brca1 cKO and Brca2 cKO mutants." (PMID 33854442, 2021). "Since we previously reported that both BRCA1 and BRCA2 are required for craniofacial bone formation, these two DDR components provide us with a premise to examine whether dysregulation of DDR via the BRCA1 or the BRCA2 pathway leads to cleft palate." (PMID 33854442, 2021). "It remains to be determined whether TCOF1, BRCA1, and BRCA2 genetically interact in palate development, and for this reason it is important to study how these specific DDR-related elements are involved in the etiology of cleft palate." (PMID 33854442, 2021).
colorectal polyp (1 paper, 2020). "One frameshift mutation in BRCA2 and one frameshift mutation in the CHEK2 gene were found in a normal control and two colorectal polyp patients, respectively." (PMID 33260537, 2020).
cyst (1 paper, 2021). A sac-like closed membranous structure that may be empty or contain fluid or amorphous material. "Cluster 7 was annotated as proliferating cholangiocytes given its high G2/M cell cycle score and expression of BRCA2, CDC6 and CDK1 in both monolayer and cyst cells." (PMID 34764255, 2021).
dermatomyositis (1 paper, 2025). Dermatomyositis (DM) is a type of idiopathic inflammatory myopathy characterized by evocative skin lesions and symmetrical proximal muscle weakness. "In addition, genetic variations in several genes, including PDE4DIP and BRCA2, were commonly detected in cfDNA from dermatomyositis patients." (PMID 40599779, 2025).
duodenal carcinomas (1 paper, 2025). "Specifically, three patients (4%) with duodenal carcinomas harbored a germline variant in BRCA2 of clinical significance." (PMID 40205657, 2025).
endometrial ovarian cancer (1 paper, 2024).
endometrioid ovarian cancers (1 paper, 2015). "This mutation was also the most common mutation found in our previous study of 74 women with serous and endometrioid ovarian cancers screened for specific BRCA1/BRCA2 mutations." (PMID 25884701, 2015).
endothelial dysfunction (1 paper, 2020). In vascular diseases, endothelial dysfunction is a systemic pathological state of the endothelium (the inner lining of blood vessels) and can be broadly defined as an imbalance between vasodilating and vasoconstricting substances produced by (or acting on) the endothelium. "Loss of BRCA2 in endothelial cells significantly exacerbated oxLDL‐induced DNA damage and apoptosis indicating that BRCA2‐mutation positive individuals might be at increased risk of endothelial dysfunction–associated diseases." (PMID 32638521, 2020). "As a next step, we proceeded to silence the BRCA2 gene to assess its significance in the setting of endothelial dysfunction." (PMID 32638521, 2020). "However, the specific roles of BRCA2 in endothelial dysfunction and atherogenesis remain unknown." (PMID 32638521, 2020).
esophagogastric adenocarcinomas (1 paper, 2022). "The remaining two BRCA2 germline carriers presented with lung and esophagogastric adenocarcinomas, both tumor types not previously associated with a BRCA-mediated phenotype." (PMID 36418296, 2022).
familial disease (1 paper, 2009). "The vast majority of familial disease is associated with a low penetrant polygenic aetiology that conveys lifetime risks somewhere below 30%, and only a small proportion are carriers of the highly penetrant mutations of BRCA1 or BRCA2, in whom the lifetime risks are quite substantial." (PMID 19457262, 2009).
Familial Temporal Lobe Epilepsy (1 paper, 2022). "The remaining three genes KMT2C, RELN, and BRCA2, had been previously associated with Kleefstra syndrome (OMIM #617768), Familial Temporal Lobe Epilepsy (OMIM #616436), and with different types of cancer, respectively." (PMID 36568968, 2022).
familial Wilms tumor (1 paper, 2023). "WAGR, DDS, familial Wilms tumor, Pearlman syndrome, mosaic variegated aneuploidy, and Fanconi anemia D1 (biallelic BRCA2 mutations) are among the syndromes with a high risk (>20%) of developing WT." (PMID 36831633, 2023).
follicular lymphoma (1 paper, 2026). Follicular lymphoma is a form of non-Hodgkin lymphoma characterized by a proliferation of B cells whose nodular structure of follicular architecture is preserved. "While, BRCA2 polymorphisms have similarly been linked to an increased risk of follicular lymphoma." (PMID 41399670, 2026). "Likewise, BRCA2 polymorphisms similarly increased follicular lymphoma risk." (PMID 41399670, 2026).
G6PD deficiency (1 paper, 2022). An X-linked genetic condition caused by alterations in the gene G6PD that result in moderately to severely decreased activity levels of the enzyme glucose-6-phosphate dehydrogenase. "We also did not include secondary findings, which included a diagnosis of G6PD deficiency in an infant that did not explain the infant’s presentation, and a pathogenic BRCA2 variant identified in a parent." (PMID 36064943, 2022).
Helicobacter pylori (1 paper, 2025). "It is possible that the increased levels of baseline DNA damage observed in BRCA1 and BRCA2 carriers acts a primer for gastric carcinogenesis, which upon addition of a second insult, such as a Helicobacter pylori (H. pylori) infection, may then more aggressively drive gastric carcinogenesis." (PMID 41256354, 2025).
hemophilia A (1 paper, 2021). The most common form of hemophilia characterized by spontaneous or prolonged hemorrhages due to factor VIII deficiency. "For example, haplotype analysis revealed three founder mutations (BRCA1 c.68_69delAG, c.5266dupC, and BRCA2 c.5946delT) in the Ashkenazi Jewish population, and a recurrent F8 mutation (c.6046C>T) causing hemophilia A in a northern Italian population." (PMID 34630384, 2021).
herpesvirus infections (1 paper, 2023). "Immunodeficiencies in BRCA1 and BRCA2 mutants may allow for the reactivation of latent EBV infections or new herpesvirus infections." (PMID 37241036, 2023).
hypopharyngeal squamous cell carcinoma (1 paper, 2020). "Pathogenic germline BRCA2 variants may be associated with an increased risk of hypopharyngeal squamous cell carcinoma that is more responsive to chemoradiation and chemotherapeutics targeting defective double-strand DNA repair." (PMID 33489192, 2020).
insulinomas (1 paper, 2017).
laryngeal tumors (1 paper, 2020). "In contrast to laryngeal tumors in TCGA, our cohort contained recurrent focal copy loss in genes associated with DNA damage repair (ATM, ATR, and BRCA2)." (PMID 33105726, 2020).
Leukopenia (1 paper, 2019). "Leukopenia was the most common severe toxicity, occurring in 7% and 8% of BRCA1 carriers and wild‐type (P = .58) and 15% and 10% of BRCA2 carriers and wild‐type (P = .24), respectively." (PMID 31407530, 2019).
lobular neoplasia (1 paper, 2017). A spectrum of non-invasive neoplastic lesions that arise from the terminal ductal lobular units of the breast. "Therefore, it is recommended that women with atypical ductalhyperplasia or lobular neoplasia undergo screening in a mannersimilar to that recommended for women with BRCA1 or BRCA2 genemutations." (PMID 28894332, 2017).
lymphoblastic leukemias (1 paper, 2012). "Less than ten cases of lymphoblastic leukemias have been reported in FA, which have been mostly of T-lineage, and appear to be limited to patients with mutations in FANCD1/BRCA2 and FANCD2." (PMID 22675616, 2012).
malignant mesothelioma (1 paper, 2023). A malignant neoplasm of the pleura or peritoneum, arising from mesothelial cells. "The aim of this study is to analyze the prevalence of somatic mutations in BRCA1 and BRCA2 in malignant mesothelioma and their putative impact on protein properties." (PMID 37020472, 2023). "This translates to a prevalence of 8.1% for BRCA2 variants in malignant mesothelioma compared to 2.1% for BRCA1 in this US based study." (PMID 37020472, 2023). "Similar to these BRCA1 and BRCA2 associated malignancies, malignant mesothelioma patients with germline BRCA mutations are reported to have improved survival and better response to cisplatin-based regimens as well as benefit from PARPi therapy." (PMID 37020472, 2023). "The aim of this study is to analyze the prevalence and frequency of somatic mutations in well-known cancer susceptibility genes, BRCA1 and BRCA2 in a small cohort of malignant mesothelioma patients and explore its putative impact on protein properties contributing to cancer pathogenicity." (PMID 37020472, 2023). "In the light of growing significance of somatic BRCA mutations, this study investigated the frequency of somatic BRCA1 and BRCA2 variants in a small cohort of malignant mesothelioma patients and found BRCA2 somatic variants to be much more common than BRCA1 variants." (PMID 37020472, 2023). "BRCA2 somatic variants were identified in 22% cases of malignant mesotheliomas in this study." (PMID 37020472, 2023). "However, as seen in both studies, BRCA2 is altered more frequently than BRCA1 in malignant mesothelioma." (PMID 37020472, 2023). "Eighteen cases of malignant mesothelioma were retrieved from the archives and for next generation sequencing analysis of BRCA1 and BRCA2 genes." (PMID 37020472, 2023). "A total of eighteen cases of malignant mesothelioma were analyzed for genetic alterations in BRCA1 and BRCA2 genes in this study." (PMID 37020472, 2023).
marginal zone lymphoma (1 paper, 2024). A usually indolent mature B-cell lymphoma, arising from the marginal zone of lymphoid tissues. "CGP additionally resulted in genetic counseling consultation for three patients: one patient with CLL who was found to have a BRCA2 mutation, one patient with CLL who was found to have an MSH6 mutation, and one patient with marginal zone lymphoma who was found to have a VHL mutation." (PMID 39449302, 2024).
Medullary carcinoma of the breast (1 paper, 2005). "Medullary carcinoma of the breast is not common (2% to 3%) in patients with BRCA2 mutations and those with no known germline gene alteration." (PMID 16168118, 2005).
mucoepidermoid carcinoma (1 paper, 2022). A carcinoma morphologically characterized the presence of cuboidal mucous cells, goblet-like mucous cells, squamoid cells, cystic changes, and a fibrotic stromal formation. "One of the BRCA2 mutations, specifically c.5511delT (p.Phe1837LeufsX3), was a novel germline mutation, not previously reported in any database, previously observedas somatic mutation in tissue of mucoepidermoid carcinoma." (PMID 35205366, 2022).
mucosal melanoma (1 paper, 2019). A melanoma that arises from a mucosal site. "Prior to our study, BRCA1 and BRCA2 have not been associated with mucosal melanoma and thus we extend the list of genes linked to this disease." (PMID 30664638, 2019).
neuroblastic tumor (1 paper, 2021). A group of nervous system tumors which display neuronal differentiation. "However, there was no report that BRCA2-N372H was associated with neuroblastic tumors." (PMID 34367235, 2021).
neutropenia (1 paper, 2017). A decrease in the number of neutrophils found in the blood. "The study was stopped early after 13 patients (BRCA1 + n = 10; BRCA2 + n = 3) were accrued within 8 months with no grade 4 toxicities and only one patient requiring dose reduction due to grade 3 neutropenia." (PMID 29238749, 2017).
Oral leukoplakia (1 paper, 2025). A thickened white patch on the oral mucosa that cannot be rubbed off. "Studies on oral leukoplakia (OLK) further suggest that BRCA1 and BRCA2 expression levels may distinguish high-risk dysplastic lesions that progress to carcinoma from those that remain benign." (PMID 40224184, 2025).
oropharyngeal squamous cell carcinoma (1 paper, 2023). "The HPV-positive oropharyngeal squamous cell carcinoma cell line, UPCI-SCC90, and the HNSCC cell line, UPCI-SCC154, were reported to harbour reduced levels of BRCA2 and other DNA repair proteins, in comparison to HPV-negative cell lines." (PMID 37113717, 2023).
ovarian carcinosarcoma (1 paper, 2020). A highly aggressive malignant neoplasm arising from the ovary. "In this work, we identified a BRCA1/BRCA2 deleterious variant frequency of 50% (2/4) in ovarian carcinosarcomas." (PMID 32850417, 2020).
ovarian dysfunction (1 paper, 2025). The inability of the ovaries to function. "It further shows that ovarian dysfunction, which is more pronounced than the influence of BRCA2 mutations, is largely influenced by BRCA1 polymorphisms." (PMID 40385922, 2025).
parasitemia (1 paper, 2022). "Brca2 KO in P. berghei resulted in reduced parasitemia, with an increase in counts at the ring stage and a decrease at the trophozoite stage, a decrease in oocyst formation, a decrease in the number of oocytes and a reduction in ookinete development." (PMID 35804459, 2022).
PEComas (1 paper, 2024).
Pruritus (1 paper, 2022). Pruritus is an itch or a sensation that makes a person want to scratch. "We identified several pruritus-associated genes increased by IDL, IDC and IDL + IDC (e.g., BRCA2, KRT5, TCF4), as well as several such genes decreased by IDL, IDC and/or IDL + IDC (e.g., IL2RG, TRPV3, TNFSF15, IL17RC)." (PMID 36430783, 2022).
psoriasis (1 paper, 2011). An autoimmune condition characterized by red, well-delineated plaques with silvery scales that are usually on the extensor surfaces and scalp. "Thus, "Jak-STAT signaling pathway", "TNFR2 signaling Pathway" and "Role of BRCA1, BRCA2 and ATR in Cancer Susceptibility" are involved in the regulation of cellular responses to cytokines with the aim to providing an insight to the molecular mechanism involved in psoriasis." (PMID 21226955, 2011).
sebaceous breast carcinoma (1 paper, 2025). A very rare breast adenocarcinoma with sebaceous differentiation. "We report a case of sebaceous breast carcinoma in a Japanese man with a BRCA2 pathogenic variant." (PMID 39980666, 2025).
seminoma (1 paper, 2024). A radiosensitive malignant germ cell tumor found in the testis (especially undescended), and extragonadal sites (anterior mediastinum and pineal gland). "The only CNA event uniquely enriched in seminomas was a recurrent LOH spanning BRCA2 (chr13:18–114 Mb)." (PMID 39461959, 2024).
Sepsis (1 paper, 2020). Sepsis is defined as life-threatening organ dysfunction caused by a dysregulated host response to infection. "Mutant mice of Brca2 had reduced life spans, possibly because of impaired DNA repair function, resulting in early onset of cancer and sepsis." (PMID 32607209, 2020).
situ breast cancer (1 paper, 2022).
small cell carcinoma of the cervix (1 paper, 2021). "A case report demonstrated promising results using PARP inhibitor in a small cell carcinoma of the cervix patient with somatic BRCA2 gene mutation." (PMID 34245124, 2021).
soft tissue tumor (1 paper, 2021). "Among these, BRCA2, ATM, and PALB2 genes had higher mutation rates of ≥4%, while in mCRPC, 19.3% of aberrations in BRCA2, BRCA1, and ATM genes were found in bone or soft tissue tumor biopsies that were substantially more frequently compared to those in primary PC tissues." (PMID 34769200, 2021).
spinal chordoma (1 paper, 2024). A slow-growing malignant bone tumor arising from the remnants of the notochord and occurring in the spine. "A 10-year-old male with a conventional lumbar spinal chordoma was found to harbor a pathogenic variant in the BRCA2 gene (c.4478_4481delAAAG/p.E1493fs*); his family history was non-contributory." (PMID 38700789, 2024).
spindle cell tumors (1 paper, 2024).
T cell deficiency (1 paper, 2022). "Their study suggested that individuals with a single BRCA2 allelic mutation could also suffer from T cell deficiency." (PMID 35626055, 2022). "The implication of BRCA2 mutations on T cell deficiency provides an avenue for immunotherapies." (PMID 35626055, 2022).